PHLDB2 (pleckstrin homology like domain family B member 2)
Description:
Seems to be involved in the assembly of the postsynaptic apparatus. May play a role in acetyl-choline receptor (AChR) aggregation in the postsynaptic membrane (By similarity).
Synonyms: LL5B; LL5beta; FLJ21791
Tractability: Antibody: UniProt places it where antibodies can reach, with high confidence; its Gene Ontology location is reachable by antibodies, with high confidence; the Human Protein Atlas places it where antibodies can reach. PROTAC: ubiquitination databases record sites on it; its protein half-life has been measured.
Gene: Protein-coding gene on chromosome 3 (111,732,403 to 111,976,837, forward strand). Ensembl gene ENSG00000144824.
Subcellular location: Cytoplasm; Cytoplasm, cell cortex; Membrane; Cell projection, podosome
Subcellular location (Human Protein Atlas): Cytosol; Plasma membrane
Gene Ontology:
Molecular function: cadherin binding; protein binding
Biological process: basement membrane organization; establishment of protein localization; microtubule cytoskeleton organization; negative regulation of focal adhesion assembly; negative regulation of stress fiber assembly; negative regulation of wound healing, spreading of epidermal cells; establishment or maintenance of cell polarity; cell migration; establishment of cell polarity
Cellular component: basal cortex; cell cortex; cell leading edge; cytoplasm; cytosol; focal adhesion; membrane; plasma membrane; podosome; microtubule associated complex
Genetic constraint (gnomAD): Loss-of-function variants: 67 observed, 114.51 expected, observed/expected ratio (o/e) 0.59, 90% interval 0.48 to 0.72. The upper end of that interval is the gene's LOEUF score, 0.72, which puts it in group 2 of 6, group 1 being the genes least tolerant of losing a copy. Missense variants: 1,375 observed, 1,496.2 expected, observed/expected ratio (o/e) 0.92, 90% interval 0.88 to 0.96. Synonymous variants: 523 observed, 540.45 expected, observed/expected ratio (o/e) 0.97, 90% interval 0.9 to 1.04.
Homologues: Orthologues: chimpanzee PHLDB2 (99% identical), macaque PHLDB2 (98% identical), pig PHLDB2 (91% identical), rabbit PHLDB2 (91% identical), guinea pig PHLDB2 (91% identical), rat Phldb2 (87% identical), mouse Phldb2 (87% identical), dog PHLDB2 (80% identical), zebrafish phldb2b (46% identical), zebrafish phldb2a (43% identical), Drosophila melanogaster dos (9% identical), Caenorhabditis elegans soc-1 (5% identical). Paralogues in human: PHLDB1 (37% identical), PHLDB3 (18% identical), GAB1 (8% identical), GAB2 (8% identical), GAB3 (7% identical), GAB4 (5% identical), PLEKHS1 (5% identical).
Diseases named in the same sentence as PHLDB2 in open-access papers:
PHLDB2 is named in the same sentence as 28 diseases in open-access papers, as found by Europe PMC text mining. Sharing a sentence is not in itself a finding about the gene and the disease. The quoted sentences say what the papers report.
colon cancer (5 papers, 2018 to 2021). "Our previous report also indicates that PHLDB2 overexpression counteracts the inhibitory effects of miR-29c-3p in cell migration and invasion, and also is associated with poorer metastasis-free survival of colon cancer patients." (PMID 31346319, 2019). "PHLDB2, short for Pleckstrin Homology-Like Domain Family B Member 2, has been reported to regulate cell migration, adhesion, and invasion of colon cancer cell lines." (PMID 33452458, 2021). "The results clearly showed that PHLDB2 depletion attenuated colon cancer cell migration and invasion facilitated by TGF-β." (PMID 31346319, 2019). "We also demonstrated that PHLDB2 knockdown mediated by siRNA was sufficient to attenuate colon cancer cell migration and invasion, as well as E-Cadherin reduction, by TGF-β treatment." (PMID 31346319, 2019). "However, the role of PHLDB2 in human cancer metastasis, especially in colon cancer, still remains elusive." (PMID 31346319, 2019). "MiR-29c-3p by targeting PHLDB2 could suppress colon cancer cell invasion and migration." (PMID 33954114, 2021). "Meanwhile, for GO enrichment analysis for down regulated genes, genes such as GSN, FSCN1, and PHLDB2 were important for the invasion of many cancer types such as pancreatic cancer, bladder cancer, and colon cancer cells, but these genes may be involved in the invasion of GBM." (PMID 31137733, 2019). "In line with our previous finding, these data suggest that in colon cancer cells, EMT induction by two important pathways, TGF-β and EGF, transcriptionally activates PHLDB2 expression." (PMID 31346319, 2019). "Our findings suggest that PHLDB2 is a downstream effector of EMT pathway and may present as an important biomarker for colon cancer prognosis and a target for colon cancer intervention." (PMID 31346319, 2019). "PHLDB2 is required for cell migration and invasion of the HCT-116 colon cancer cell line." (PMID 30131849, 2018).
colorectal cancer (4 papers, 2018 to 2024). A primary or metastatic malignant neoplasm that affects the colon or rectum. "Together, these results indicate that high level of PHLDB2 is associated with poorer clinical outcomes and tumor invasiveness in colorectal cancer patients." (PMID 31346319, 2019). "High expression of PHLDB2 in colorectal cancer is also associated with shorter metastasis-free survival." (PMID 30131849, 2018). "Interestingly, PHLDB2 was implicated in other kinds of cancer, such asrenal cell carcinoma and gastric and colorectal cancer." (PMID 34337001, 2021). "The upregulation of PHLDB2 has been observed in various cancers, including colorectal cancer, gastric cancer, and lung adenocarcinoma." (PMID 38397469, 2024). "Our findings underscore the importance of PHLDB2 in EMT and metastasis, and therefore provide the rationale for determining PHLDB2 as a biomarker and a target in colorectal cancer." (PMID 31346319, 2019). "The RNA-seq and clinical data of colorectal cancer patients from the Cancer Genome Atlas (TCGA) were analyzed for correlations between PHLDB2 and clinical outcomes as well as epithelial–mesenchymal transition (EMT) markers." (PMID 31346319, 2019). "While PHLDB2 is an important protein involved in focal adhesion disassembly in migrating cells, we next sought to investigate if PHLDB2 is correlated with any EMT markers in the same set of colorectal cancer patients." (PMID 31346319, 2019). "Notably, a recent report revealed that PHLDB2 plays a critical role in cetuximab resistance and is suggested as a potential therapeutic target for colorectal cancer." (PMID 38397469, 2024). "Our present study revealed the important role of PHLDB2 in clinical outcomes and EMT from a large cohort of colorectal patients, and therefore provide the rationale to determine PHLDB2 as a valuable biomarker and/or to develop strategies to target PHLDB2 for colorectal cancer intervention." (PMID 31346319, 2019). "In the present study, by analyzing human colorectal cancer database from the Cancer Genome Atlas, we demonstrate not only the association of PHLDB2 expression with patient prognosis, but also the high correlation between PHLDB2 and multiple EMT markers." (PMID 31346319, 2019). "Moreover, researchers have hypothesized that PHLDB2 could serve as a valuable biomarker and a potential target for interventions in colorectal cancer." (PMID 38397469, 2024). "MALL, PHLDB2 and other genes responsive to APC are consistent with the emerging role of canonical WNT signaling targets in colorectal cancer invasion and progression, in addition to the better-characterized role of the pathway in colorectal tumor initiation." (PMID 30131849, 2018).
gastric cancer (3 papers, 2024 to 2025). A primary or metastatic malignant neoplasm involving the stomach. "In gastric cancer, NR2F1-AS1 acts as an EMT-inducing lncRNA that enhances cell motility via the miR-29a/VAMP7 axis, activation of AKT3 through miR-190a/PHLDB2, SPI1-mediated transcriptional upregulation of ST8SIA1, and miR-493-5p/MAP3K2 signaling." (PMID 40828427, 2025). "In gastric cancer, NR2F1-AS1 enhances cell growth through various axes, including miR-29a/VAMP7, miR-190a/PHLDB2/AKT3, SPI1/ST8SIA1, and miR-493-5p/MAP3K2." (PMID 40828427, 2025).
head and neck squamous cell carcinoma (2 papers, 2021 to 2024). A squamous cell carcinoma that arises from any of the following anatomic sites: lip and oral cavity, nasal cavity, paranasal sinuses, pharynx, larynx, and salivary glands. "However, the exploration of PHLDB2 in head and neck squamous cell carcinoma (HNSCC) is still limited in terms of expression, function, and therapeutic potential." (PMID 38397469, 2024). "In our next study, we will further investigate whether the targeted inhibition of PHLDB2 in combination with a PD-1 monoclonal antibody improves clinical outcomes in patients with head and neck squamous cell carcinoma." (PMID 38397469, 2024).
renal carcinoma (2 papers, 2021). A carcinoma arising from the epithelium of the renal parenchyma or the renal pelvis. "It was reported that L-2HG upregulated PHLDB2 to promote vasculogenic mimicry (VM) in renal cancer cell lines in a way associated with DNA methylation; the DNA methyltransferase inhibitor counteracted with L-2HG in regulating PHLDB2." (PMID 33842477, 2021). "Furthermore, we demonstrated that L‐2HG promoted vasculogenic mimicry (VM) in renal cancer cell lines through reducing the expression of PHLDB2." (PMID 33320958, 2021).
renal cell carcinoma (2 papers, 2021 to 2025). "PHLDB2 (pleckstrin homology-like domain family B member 2) contains a PH domain involved in protein complex formation and cell migration and is associated with overall survival in renal cell carcinoma." (PMID 41300790, 2025).
asthma (1 paper, 2026). "In ex vivo severe asthma bronchial biopsies, the protein levels were upregulated 1.2-fold for PHLDB2 (p = 0.2844), 2.4-fold (p < 0.01) for NEK6, and 2.0-fold for SCNN1G (p < 0.05)." (PMID 41664127, 2026).
atrial fibrillation (1 paper, 2021). A disorder characterized by an electrocardiographic finding of a supraventricular arrhythmia characterized by the replacement of consistent P waves by rapid oscillations or fibrillatory waves that vary in size, shape and timing and are accompanied by an irregular ventricular response. "Atria-Enriched GJA5, KCNA5 and NPPA, RA-Enriched HCM4, MIR100HG, REC114 and SMAD7 and Ventricles-Enriched KCNJ2, MYH7, PHLDB2, RPL2L and SLC35F1 were associated with atrial fibrillation." (PMID 34088950, 2021).
fibrosis (1 paper, 2021). the formation of excess fibrous connective tissue in an organ or tissue in a reparative or reactive process. "Even the typical phenotype of coal dust inhalation was lung fibrosis, what is the functions of PHLDB2 in fibrosis?" (PMID 34337001, 2021).
lung carcinoma (1 paper, 2021). "For the previous key findings in current study, we then asked whether PHLDB2 mutations contributed to lung cancer." (PMID 34337001, 2021). "In summary, RNA-seq-based strategies helped us identified PHLDB2 as a new lung cancer-related maker." (PMID 34337001, 2021). "By retrieving TCGA lung cancer dataset, we observed that PHLDB2 showed upregulations in males and smoker patients." (PMID 34337001, 2021). "In summary, using RNA-seq-based screening strategy, we detected that PHLDB2 might be a potential lung cancer-related marker." (PMID 34337001, 2021). "We noticed that PHLDB2 was negatively correlated with some EMT markers, suggesting that PHLDB2 might contribute to lung cancer by regulating the EMT process." (PMID 34337001, 2021). "By retrieving the TCGA public dataset, we observed that PHLDB2 was significantly decreased in lung cancer patients, while those with higher expression survived longer, suggesting PHLDB2 might play protective role in caner development." (PMID 34337001, 2021).
lymph node metastasis (1 paper, 2021). "By univariate Cox regression analysis, elder age, diffuse type, high grade, advanced T, N, and M stage, lymph node metastasis and high expression of PHLDB2 were associated with poor outcome." (PMID 33452458, 2021).
triple-negative breast carcinoma (1 paper, 2025). An invasive breast carcinoma which is negative for expression of estrogen receptor (ER), progesterone receptor (PR), and human epidermal growth factor receptor 2 (HER2). "In this study, we systematically analyzed the expression of PHLDB2 across multiple cancer types and its association with survival outcomes in triple negative breast cancer (TNBC) patients." (PMID 41319208, 2025).
vascular dementia (1 paper, 2018). A degenerative vascular disorder affecting the brain. "One example of significant differentially expressed transcripts, not detected by gene-level analyses and not identified by previous ccRCC studies, are derived from Pleckstrin homology like domain family B member 2 (PHLDB2) known commonly for its association with vascular dementia." (PMID 29805765, 2018).
cancer (9 papers, 2019 to 2025). A tumor composed of atypical neoplastic, often pleomorphic cells that invade other tissues. "While PHLDB2 has been conventionally implicated in cancer prognosis through its role in cell migration, its potential capacity for phase separation remains unreported to date." (PMID 41319208, 2025). "In the TCGA mutation database, we found 29 mutations in the coding and flanking regions of PHLDB2, representing 2.74% of 1,059 cancer patients." (PMID 34337001, 2021). "PHLDB2, also known as pleckstrin homology-like domain family B member 2, has been implicated in the several other types of cancers." (PMID 34337001, 2021). "In the single-cell sequencing data set (GSE81861), PHLDB2 was positively correlated to cancer-associated fibroblasts (CAFs) about the EMT state of CRC." (PMID 34526059, 2021). "However, it remains largely unknown whether and how PHLDB2 is implicated in clinical cancer patients and the underlying mechanisms, especially in colorectal tumors." (PMID 31346319, 2019). "We analyzed PHLDB2 expression across various cancer types and found significantly lower expression in tumor tissues compared to normal tissues in most cancers." (PMID 41319208, 2025). "In terms of functionality, the genetic reduction in PHLDB2 dampened the EMT phenotype of cancer cells and boosted CD8+T cell function." (PMID 38397469, 2024). "The mounting evidence strongly supports the crucial role of PHLDB2 in tumorigenesis and the prognosis of cancer patients." (PMID 38397469, 2024). "Our analysis revealed a noteworthy upregulation of PHLDB2 in the majority of human cancers, including HNSCC." (PMID 38397469, 2024). "To investigate the expression patterns of PHLDB2 in HNSCC, we initially assessed the mRNA expression of PHLDB2 in various types of cancers and normal tissues from different cancer populations, utilizing data from the TCGA database." (PMID 38397469, 2024). "By immunohistochemistry (IHC), PHLDB2 was found to be predominantly located in the cytoplasm of the cancer cells in both intestinal and diffuse-type GC of Hong Kong cohort." (PMID 33452458, 2021). "PHLDB2 showed significantly lower expression in cancer patients when compared with controls (p = 4.5 × 10−73)." (PMID 34337001, 2021). "These functional characteristics suggest a potentially important role of PHLDB2 in cancer cell mobility, and ultimately metastatic progression." (PMID 31346319, 2019). "Furthermore, recent research has highlighted the possible involvement of PHLDB2 in cancer cell mobility and the process of the epithelial–mesenchymal transition (EMT), which ultimately leads to metastatic progression." (PMID 38397469, 2024). "Meanwhile, pan-cancer analysis suggested PHLDB2 upregulated or down regulated in different types of cancer, implying that PHLDB2 might contribute to different cancers with different functions." (PMID 34337001, 2021). "PHLDB2, a member of the PHLDB family, has garnered relatively little attention in cancer research." (PMID 41319208, 2025). "Silencing PHLDB2 significantly impeded cancer cell migration, while our in vitro experiments revealed no impact of PHLDB2 on cell proliferation in HNSCC cells." (PMID 38397469, 2024). "In addition, we show that PHLDB2 is responsive to EMT induction and at least partially required for cancer cell invasion and migration promoted by TGF-β, likely through interacting with MDM2 to facilitate E-Cadherin degradation." (PMID 31346319, 2019). "Furthermore, PHLDB2 was significantly higher in smoker cancer patients than in nonsmokers (p = 1.0 × 10−4)." (PMID 34337001, 2021). "Even PHLDB2 might be holding the same function in EMT, while the network of controlling EMT is really far beyond the scope of our current study and also the other types of cancer." (PMID 34337001, 2021).